IGKV1OR-2 (immunoglobulin kappa variable 1/OR-2 (pseudogene))
Synonyms: IGKV1/OR-2; IGKV1OR2; IGKVPZ2
Gene: Immunoglobulin variable (V) pseudogene on chromosome 9 (64,765,054 to 64,765,535, reverse strand). Ensembl gene ENSG00000156755.
Diseases named in the same sentence as IGKV1OR-2 in open-access papers:
IGKV1OR-2 is named in the same sentence as 3 diseases in open-access papers, as found by Europe PMC text mining. Sharing a sentence is not in itself a finding about the gene and the disease. The quoted sentences say what the papers report.
tumor (1 paper, 2023). "Among TME-related prognostic signature, KLRB1, SCL27A2, PXDNL, LINC02038, IGHV1-12, IGKV1OR2-108 were directly related to tumor immunity to a certain extent, reflecting the characteristics of natural killer cells, natural killer T cells and other immune cells." (PMID 36869083, 2023). "Therefore, the up-regulated key TME-related genes SLC27A2, KLRB1, IGKV1OR2-108 and IGHV1-12 in the low-risk score group inhibit tumor progression by affecting the secretion of neutrophils, NK cells and immunoglobulin." (PMID 36869083, 2023).
IGKV1OR-2 also shares sentences with these, for which no sentence is quoted: cancer (1 paper); type 2 diabetes (1).